IL33 (interleukin 33)
Diseases named in the same sentence as IL33 in open-access papers (continued):
Sharing a sentence is not in itself a finding about the gene and the disease.
asthma (continued). "Notably, among the predicted upstream regulators were IL-33 and the transcription factor retinoic acid-related orphan receptor α (RORA), both shown to significantly contribute to the pathogenesis of asthma in a recent genome-wide association study." (PMID 26740570, 2016). "Il-33 signaling mediates allergen-induced Th2 cytokines which induce asthma." (PMID 26999172, 2016). "Interleukin-33 (IL-33), a cytokine of the IL-1 family, is expressed in epithelial barrier tissues and lymphoid organs and plays important roles in type-2 innate immunity, human asthma, and parasitic infection." (PMID 27900334, 2016). "Therefore we determined BAL fluid and endobronchial biopsy specimen IL-33 levels in the children with severe asthma and showed that they were higher in patients with SAFS." (PMID 25746970, 2015). "Moreover, elevated levels of IL-33 have been demonstrated in situ in bronchial epithelium as well as bronchial smooth muscle cells from subjects with severe asthma, implicating IL-33 in asthma pathogenesis." (PMID 26318341, 2015). "Additionally, disruption of IL-33/ST2 signalling in vivo during the course of experimental asthma or anaphylaxis reduced the severity of disease." (PMID 25683166, 2015). "This suggested that IL-33 might be important in mediating fungal sensitization in pediatric patients with severe asthma." (PMID 25746970, 2015). "Aberrant IL-33 expression in patients with autoimmune disorders suggests the participation of this inflammatory cytokine in the initiation and progression of diseases including asthma, systemic lupus erythematosus and inflammatory arthritis." (PMID 26677348, 2015). "Bronchial epithelium and ASM expressed IL-33 with the latter in asthma correlating with AHR." (PMID 25683166, 2015). "In addition, several animal models indicate that IL-33 and its receptor play an important role in the development of asthma and allergic airway inflammation." (PMID 26214807, 2015). "We hypothesized that fungal sensitization in children with severe therapy-resistant asthma (STRA) is associated with more severe disease and is mediated by the innate cytokine IL-33." (PMID 25746970, 2015). "We sought to determine whether fungal sensitization in children with severe therapy-resistant asthma is mediated by IL-33." (PMID 25746970, 2015). "During an asthma exacerbation, the exact kinetics of IL-33 release are unknown and timing of patient sampling is variable." (PMID 26365875, 2015). "Thus, the epithelial-derived cytokine IL-33 appears to act on a variety of inflammatory and structural cell types to promote the development of asthma." (PMID 26214807, 2015). "This suggests that IL-33 may present an important target to modulate mast cell–ASM crosstalk in asthma." (PMID 25683166, 2015). "However, in Th2-mediated inflammatory diseases, such as asthma, rheumatological diseases, and inflammatory skin disorders, IL-33 appears to have pro-inflammatory effects and exacerbates the diseases." (PMID 25658420, 2015). "Additionally, these results were also confirmed by elevated IL-33 expression in bronchial epithelial cells of asthma patients compared to healthy individuals by immuno-histochemical studies." (PMID 26425339, 2015). "Therefore, HDM-induced AHR in our murine model of asthma appears to affect both the proximal and distal airways and is highly dependent on IL-33." (PMID 26214807, 2015). "This Alternaria-specific capacity to initiate the rapid and robust IL-33–dependent pulmonary allergic inflammation may define why patients with severe asthma exacerbations have frequently been exposed to Alternaria." (PMID 24636086, 2014). "Because IL-13 is an important cytokine involved in airway remodeling in asthma, IL-33 might augment airway remodeling through its enhancement of IL-13 production from fibrocytes without allergen stimulation." (PMID 24822215, 2014). "Also in our asthma models, IL-33 is released by stromal cells, such as epithelial and smooth muscle cells, after HDM provocation." (PMID 24453940, 2014).
asthma (continued). "IL-33 might play a pivotal role in the pathophysiology of refractory asthma characterized by persistent symptoms despite use of multiple regular asthma therapies, including inhaled corticosteroids and CysLTR antagonist." (PMID 24822215, 2014). "Furthermore, since lower levels of 25(OH) Vit D and high levels of IL-31 and IL-33 are associated with Th2 immunity of allergic disease, we hypothesized a potential interaction between these markers and clinical and functional parameters in asthma and rhinitis." (PMID 25061262, 2014). "IL-33 is potentially important in the pathogenesis of exacerbations of asthma." (PMID 25264520, 2014). "However, by doing so, IL-33 contributes to the pathogenesis of asthma, atopic dermatitis, and allergic conjunctivitis 18,27." (PMID 25116404, 2014). "Interestingly, IL33 is found in the network, which was differentially expressed between upper and lower airways of patients with allergic rhinitis with asthma." (PMID 24282527, 2013). "Moreover, genetic dysregulation of the IL-33/IL1RL1 axis appears to be involved in conferring predisposition to several multifactorial diseases, such as Alzheimer’s disease, asthma, nasal polyposis, allergic rhinitis, and atopic dermatitis." (PMID 23634226, 2013). "Consequently, mice overexpressing IL-33 were reported to display spontaneous airway and lung inflammation, whereas blocking the IL-33/ST2 axis decreased inflammation in an experimental murine model of asthma." (PMID 23766561, 2013). "Higher IL-33 expression occurs in patients with asthma and in murine models of asthma." (PMID 23496815, 2013). "Although increased levels of IL-33 protein in tissues and in circulation have been reported in several diseases such as asthma, rheumatologic pathologies, inflammatory bowel and skin diseases, reports showing cellular release of IL-33 after stimulation are scarce." (PMID 23567618, 2013). "In the context of our previous report that activated AM from an acute exacerbation are able to stimulate Th2 cytokine secretion by primed CD4+ T cells, these results strongly suggest a role for these AM in driving IL-33-dependent inflammation in an acute exacerbation of asthma." (PMID 23936781, 2013). "We reasoned that although ORMDL3 levels may not affect the production of IL-6 or IL-8 cytokines, perhaps they were impacting gene expression of other important immune genes, such as IL-33, IL-25 and TSLP, which have all been implicated in asthma pathogenesis." (PMID 23369242, 2013). "Thus, IL-33 acts as an inflammatory cytokine in Th2-type immune responses during asthma or atopic dermatitis and seems to be responsible for the host defense against helminth infections." (PMID 23567618, 2013). "High levels of IL-33 were detected in patients with asthma or allergic rhinitis." (PMID 23855879, 2013). "In particular, IL-33 has been found to pivotally contribute to asthma-induced pathology." (PMID 23087690, 2012). "Treatment of OVA-induced AHR mice with ST2 and IL-33 blocking antibodies was also found to ameliorate airway inflammation, which highlights the great promise that IL-33 neutralizing therapies hold in the treatment of asthma." (PMID 23087690, 2012). "IL‐33 plays a central role in the generation of both these cell types, indicating that biologics targeted at this alarmin may be particularly useful in uncontrolled asthma patients with profound Tc2 cell and/or CD45RO+ ILC2 activity." (PMID 40016948, 2025). "TSLP and IL-33 are key players in both T2 and non-T2 inflammation, and biologics targeting these alarmins, such as tezepelumab, astegolimab, and ecaleralimab, represent promising future therapeutic options for a broader range of severe asthma patients, including those with non-T2 phenotypes." (PMID 40486460, 2025).
asthma (continued). "Although Th2 cells are at the heart of asthma pathogenesis, group 2 innate lymphoid cells (ILC2s) have gained interest in recent years because of their ability to produce type 2 cytokines and because they can be activated by the epithelial-derived alarmins IL-33, IL-25, and TSLP (left)." (PMID 41145900, 2025). "Notably, IL‐33 has been targeted in several clinical trials for conditions such as asthma, chronic obstructive pulmonary disease, and atopic dermatitis, which offers potential therapeutic strategies for targeting IL‐33 in the context of pathological new bone formation." (PMID 40091508, 2025). "In addition, IL-33 has been identified as a major interleukin in asthma pathology." (PMID 40777015, 2025). "According to reports, GSDMB may control the release of TSLP, IL-33, and IL-25, which are critical for the pathophysiology of asthma, by encouraging the infiltration of neutrophils and eosinophils in the inflamed airways; this is more pronounced in individuals with the T/C or T/T genotype." (PMID 39906448, 2025). "Thus, TSLP and IL-33 play a key role in immune hyperresponsiveness that mediates asthma attacks." (PMID 41293155, 2025). "However, IL-33 driven inflammation is a double-edged sword capable of prolonging inflammation and inducing tissue damage, as portrayed in asthma and allergy, and precise modulation is essential to sustain homeostasis, and herein lies the potential therapeutic role of miRNAs." (PMID 39591475, 2024). "Studies by Kim A.T. Verheijden and colleagues in HDM-induced asthma mouse models demonstrated that adding galacto-oligosaccharides (GOS) to infant formula diets had intestinal and immune modulatory effects, attenuating IL-33 expression associated with intestinal barrier dysfunction." (PMID 39301028, 2024). "We hypothesised that different isoforms of IL33, that may be more prevalent in the airways of patients with asthma, may differentially activate IL1RL1 and that asthma‐associated IL1RL1 nonsynonymous variation may further modify the magnitude of this signalling response." (PMID 39301832, 2024). "Strategies aimed at blocking IL-33 or modulating its downstream effects hold significant therapeutic potential for managing and potentially preventing the progression of respiratory diseases characterized by type 2 inflammation, such as asthma, COPD, and allergic rhinitis." (PMID 39301028, 2024). "Considering the role of IL-33 and the alarmin thymic stromal lymphopoietin in activating the type 2 immune response, a combined blockade of both cytokines may be beneficial in patients with immunological conditions such as asthma or CRSwNP." (PMID 39215351, 2024). "A plausible explanation is that children with mild asthma may have low serum levels of IL-33." (PMID 38731070, 2024). "This may therefore identify patients with more IL33‐relevant asthma." (PMID 39301832, 2024). "We show that a single treatment with IL-33 and TL1A is sufficient for induction of IL-9-producing ILC2s in vivo and that endogenous IL-33 and TL1A are necessary for rapid induction of IL-9high ILC2s after a single exposure of naïve mice to A. alternata, a major asthma-associated allergen." (PMID 38597952, 2024). "Genetic association studies have uncovered those variations within the IL33 gene, the ST2 (IL1RL1) receptor, the ROR-α (RORA) transcription factor, and IL13—all pivotal in the development and activation of ILC2s—are linked to asthma with a high presence of type 2 helper T cells." (PMID 38680486, 2024). "We suggest that this novel finding may be particularly important in asthma patients that carry IL1RL1 asthma risk alleles and have a lung microenvironment that promotes elevated levels of cleaved IL33 isoforms, leading to a more IL33‐driven disease amenable to targeting." (PMID 39301832, 2024). "Therefore, the IL‐33 levels of either serum or plasma may be regarded as a useful biomarker of asthma or the degree of disease." (PMID 37102668, 2023).
asthma (continued). "Furthermore, in a model of OVA-allergic mice infected with RSV, neutralization of IL-33 significantly reduced ILC2, eosinophils, and the prototypical allergic proteins IL-5, IL-13, CCL17 and CCL22, further indicating the key role played by IL-33 in RSV-induced asthma exacerbation." (PMID 37483591, 2023). "We found that CISDs associate with the 17q21 locus (GSDMB/ZPBP2) as well as TSLP, IL33, and the gene encoding the IL33 receptor, IL1RL, which all have previously shown to be associated with asthma, and have also shown to be functionally relevant in asthma models." (PMID 36653354, 2023). "Vitamin E and selenium have been shown to affect Th2 cytokines (IL-4, IL-5, and IL-13) as well as their upstream cytokines (IL-25 and IL-33), suggesting that they may be a beneficial treatment for the management of allergic diseases such as allergic rhinitis and asthma." (PMID 37513609, 2023). "As IL-33 appears to play a role in inflammatory responses of the lung following RV exposure, newer biologic therapies targeting IL-33 signaling, such as astegolimab and itepekimab, may also be effective in preventing RV-induced asthma exacerbations and subsequent airway remodeling." (PMID 37773065, 2023). "Our data showed that airways and tissue eosinophilia, as well as the expression of total IgE, OVA‐specific IgE, IL‐13 and IL‐33 in response to OVA challenge, were inhibited by serial CSE exposure, which may be associated with difficult‐to‐treat asthma with smoking." (PMID 37963721, 2023). "Therefore, we hypothesized that IL‐33 and ILC2s play a role in asthma via the PI3K/AKT signaling pathway." (PMID 37357549, 2023). "We focused on the “Endothelial-Mast-IL33-IL1RL1” interaction, as IL33 activation by mast cells plays a significant role in airway inflammation, especially asthma; therefore, we can raise the question of whether IL33 takes part in the pathogenesis of IPF as well." (PMID 37627276, 2023). "Therefore, targeting IL-33 through different inflammatory pathways may be an advantage in treating some lung diseases such as asthma and COPD." (PMID 37240045, 2023). "Therefore, IL‐33 levels of either serum or plasma may be regarded as a useful biomarker of asthma or the degree of disease." (PMID 37102668, 2023). "Thus, among epithelial-derived cytokines, IL-33 and TSLP might contribute to ILC2-associated asthma." (PMID 37371472, 2023). "Additionally, there is evidence to suggest that IL-33 may directly affect mast cell activation, airway smooth muscle migration, and asthma phenotype." (PMID 36078171, 2022). "Furthermore, other signals (e.g., allergen) present in the tissue microenvironment may make important contributions to local IL-33 concentrations to influence MC contributions to viral-induced exacerbations of asthma." (PMID 36366528, 2022). "However, unlike IL-25 that promotes virus-linked asthma exacerbations by amplifying T2 responses, IL-33 can facilitate this process by hampering innate and adaptive Th1 and cytotoxic responses." (PMID 36311787, 2022). "Genetic polymorphisms in genes including alarmin cytokines (TSLP and IL-33) type 2 cytokines (IL-4, IL-13) and other inflammatory-related proteins (HLA, ADAM33), and vitamin D receptor have been shown to enhance, or reduce, the risk and severity of asthma in individuals." (PMID 36292755, 2022). "Another study found that miR-3934 levels in PBMCs and serum can distinguish asthma patients from controls, particularly severe asthma patients, and that miR-3934 levels in PBMCs were negatively correlated with serum levels of IL-6, IL-8, and IL-33 in asthma patients, respectively." (PMID 36459329, 2022). "In addition to asthma, the epithelial-derived alarmins IL-33, IL-25, and TSLP play important roles in the pathogenesis of other allergic diseases including allergic rhinitis, chronic rhinosinusitis, atopic dermatitis, food allergy, and allergic keratoconjunctivitis." (PMID 35406669, 2022).
asthma (continued). "IL-33 is one of the earliest cytokines released in response to stimulation with allergens, with elevated levels found in the airway secretions of patients with acute asthma, and these elevated levels of IL-33 expression in lung epithelium correlates with asthma severity." (PMID 36292755, 2022). "Since we could not define the cause of increasing amorphous substrate in his study, we think that further studies of knock-out mice are needed to define other molecules that may trigger the onset of asthma, such as IL33 and ST220, using the ultrastructural analysis methods developed in this study." (PMID 35641585, 2022). "In airway inflammation, Phase 1 and 2 clinical trials using an anti-IL-33 mAb, itepekimab, in patients with moderate to severe asthma showed decreased blood eosinophil levels and improved lung function, suggesting that IL-33 may be a promising molecular target for the treatment of allergic asthma." (PMID 36291105, 2022). "Furthermore, IL-33 levels in BALF were shown to positively correlate with the severity of asthma." (PMID 35911708, 2022). "Since IL-4, IL-5, IL-10, IL-17, and IL-33 would not be measured in peripheral blood samples, we think it is not feasible to use these cytokines in clinical practice or in the research of the underlying mechanisms of the asthma phenotypes." (PMID 36326393, 2022). "Interestingly, the increased smooth muscles in asthma might be a major source of pro-inflammatory asthma-relevant cytokines such as IL-13, IL-17, IL-22, IL-33, lymphopoietin, semaphorins, and CXC chemokines." (PMID 34834581, 2021). "However, the role of IL-33-induced type 2 inflammation in obesity-associated asthma has not yet been established." (PMID 34074279, 2021). "Interleukin-33 (IL-33) is another member of the Interleukin-1 family of cytokines that has emerged as a target of interest in a variety of inflammatory conditions including asthma, chronic obstructive pulmonary disease, and most recently Coronavirus disease 2019 (COVID-19)." (PMID 34723980, 2021). "It should be considered whether IL-33 has transcriptional repression in asthma and bronchiolitis." (PMID 33514798, 2021). "A role for IL-33 in human type 2–driven chronic airway disease was highlighted by genome-wide association studies linking IL33 and IL1RL1/ST2 with asthma and increased IL-33 in serum, sputum, or tissue from patients with asthma and patients with chronic obstructive pulmonary disease (COPD)." (PMID 33507882, 2021). "In addition to TSLP, IL-33 and IL-25 may also represent further emerging targets for novel anti-asthma treatments." (PMID 34572294, 2021). "Therefore, TSLP, IL-33, and IL-25 represent suitable targets for add-on therapies of severe asthma." (PMID 34572294, 2021). "Among the most highly replicated asthma loci are variants near the genes encoding the cytokine IL-33 on chromosome 9p24.1 and its receptor, ST2 (encoded by IL1RL1), on chromosome 2q12.1, highlighting the potential importance of this pathway in the genetic etiology of asthma." (PMID 34675193, 2021). "Since sST2 neutralizes the effect of IL-33, it is considered an anti-inflammatory factor in conditions in which IL-33 takes place in the driving inflammatory processes, such as asthma and Pso, and IL-33 neutralization may represent a novel therapeutic approach in these diseases." (PMID 33488605, 2020). "Thus, the IL-33-dependent mechanisms, specifically those activating type 2 immune responses that drive asthma, allergy, and the expulsion of helminth infections, may not be relevant to brain infection with an intracellular pathogen." (PMID 33108405, 2020). "Increased IL-33 is also commonly observed in tissues during active disease, such as in endobronchial biopsies from children with severe asthma, suggesting that IL-33 may not only participate in priming events but also in ongoing inflammatory effector responses." (PMID 31940364, 2020).